CD4 (CD4 molecule)
Diseases named in the same sentence as CD4 in open-access papers (continued):
Sharing a sentence is not in itself a finding about the gene and the disease.
Kaposi's sarcoma (continued). "Further, a CD4+ count <100/mm3 belonged to major aphthous ulcers, necrotizing ulcerative periodontitis, Kaposi sarcoma, and HSV ulcers." (PMID 25745611, 2015). "After establishment of the diagnosis of Kaposi Sarcoma, specific testing of the immune status showed normal CD4 cell counts and normal CD4/CD8 ratio." (PMID 25077599, 2014). "The main reasons for referral were advanced clinical stages (WHO stages 3 and 4, and CD4 count <50 cells/μl) in 70% of the cases, and 19% had Kaposi sarcoma." (PMID 24717189, 2014). "ES with low CD4+ T-cell counts have been described previously; one elite suppressor with a low CD4+ T-cell count developed Kaposi's Sarcoma despite undetectable viral load." (PMID 22240256, 2012). "Three months after regular HAART, she developed features of disseminated Kaposi's sarcoma involving the skin, oropharynx and lungs, despite evidence of 42% increase in CD4 cell count." (PMID 22355437, 2011). "By the early 1990s several independent studies indicated IFN-α as an efficient anti-tumor drug in HIV patients with Kaposi’s sarcoma who had CD4 counts higher than 200 cells/mm3." (PMID 32280376, 2009). "There was significantly high occurrence of oral candidiasis (P < 0.0001), which was similar to many previous studies and Kaposi sarcoma (P < 0.03) among patients with low CD4+ counts (below 200/μl)." (PMID 20101334, 2009). "A beneficial effect of IFN-α was immediately recognized in the treatment of Kaposi’s sarcoma in HIV patients in whom the number of circulating CD4 T cells was at least partially preserved." (PMID 32280376, 2009). "The dermatological manifestations have high prevalence among HIV positive subjects; of these, oral candidiasis and Kaposi's sarcoma are significantly correlated with low CD4+ counts." (PMID 20101334, 2009). "For Kaposi sarcoma, the unadjusted HR was 1.56 (95% confidence interval [CI],1.52–1.60), decreasing to 1.46 (95% CI, 1.42–1.50) after adjusting for age, sex, and calendar year, and to 1.38 (95% CI, 1.35–1.42) after further adjusting for CD4 count." (PMID 39736138, 2025). "Based on their report, it is tempting to hypothesize that EBV-SMT is similar to Kaposi sarcoma in that the tumor can be controlled after an increase in CD4 count." (PMID 35141174, 2022). "While, Kaposi sarcoma, cryptococcal and human papilloma virus related lesions are encountered in patients with low CD4 levels, the ones with good immunological status may have seborrheic dermatitis or kseroderma." (PMID 28443591, 2017). "Different studies showed an association between reduction in CD4+ count with the presence of oral Kaposi sarcoma, non-Hodgkin’s lymphoma and necrotizing ulcerative periodontitis." (PMID 25745611, 2015). "According to some authors, Kaposi’s sarcoma is not a true neoplasm, but rather a hyperplastic reaction caused by angiogenetic factors released from either CD4+ lymphocytes or viruses." (PMID 24378063, 2013). "Diseases like cytomegalovirus (CMV) retinitis, keratoconjunctival sicca, retinal and conjunctival microvasculopathy occur commonly when the CD4 cells count falls below 100 cells/mm3 and Kaposi’s sarcoma occurs when the CD4+T cells count falls below 500 cells/mm3." (PMID 23710936, 2013). "However, Kaposi's sarcoma in combination with multicentric Castleman's disease reoccurred 18 months later although CD4 counts were above 350 CD4-cells/μL at this time." (PMID 22900154, 2012). "Significant correlation with low CD4+ cell counts was found for oral candidiasis (P < 0.0001) and Kaposi's sarcoma (P = 0.03), while other disorders such as seborrheic dermatitis (P = 0.22), xerosis (P = 0.25), and onychomycosis (P = 0.08) were not statistically significant." (PMID 20101334, 2009). "Statistically significant correlation with low CD4+ cell counts was found for oral candidiasis (P < 0.0001) and Kaposi's sarcoma (P = 0.03); it was insignificant for other disorders such as seborrheic dermatitis (P = 0.22), xerosis (P = 0.25), and onychomycosis (P = 0.08)." (PMID 20101334, 2009).
Kaposi's sarcoma (continued). "On the other hand, the incidence of other NHL subtypes such as Centroblastic Diffuse Large-cell Lymphomas, along with classic Burkitt’s Lymphoma, Hodgkin’s disease, cervical cancer and, most notably, Kaposi’s sarcoma, increases in patients who have significantly higher CD4+ T-cell numbers." (PMID 21416008, 2009). "Key words:Kaposi Sarcoma, KSHV, HIV infection, CD4 count, oral lesion, oral cancer, periodontal pathogens." (PMID 35582353, 2022). "Low CD4 cell count is an independent predictor of developing ADC and NADCI: Kaposi sarcoma, non-Hodgkin lymphoma, anal cancer and Hodgkin lymphoma." (PMID 33670229, 2021). "The CD4 cell count in HIV patients with AZT and Kaposi's sarcoma-induced PRCA were 199–271 and 450 cell/mm3, respectively." (PMID 32257434, 2020). "Kaposi sarcoma is considered as a borderline malignant tumor derived from lymphatic endothelial cells and is common in advanced HIV infection with low CD4 cell count." (PMID 31827596, 2019). "Thus, low p27CA concentration in plasma may mean a positive effect of rHuIFN-α treatment, similarly to what happens in HIV patients, in which the decrease of circulating p24CA levels induced by IFN-α correlates with the increase of CD4+ T-cells and an antitumoral response against Kaposi’s sarcoma." (PMID 31514435, 2019). "In this article, we describe the coexistence of neuromeningeal cryptococcosis and gastric Kaposi’s sarcoma in a patient with HIV infection and a relatively high CD4 count, who had a fatal outcome." (PMID 30867046, 2019). "This clinical case shows that the coexistence of neuromeningeal cryptococcosis and gastric Kaposi’s sarcoma is possible in all patients with human immunodeficiency virus infection, regardless of CD4 count." (PMID 30867046, 2019). "The coexistence of neuromeningeal cryptococcosis and Kaposi’s sarcoma is not surprising in a patient with human immunodeficiency virus infection and a low CD4 count, although it is rarely described." (PMID 30867046, 2019). "Paradoxically, the administration of super physiological doses of Type-I IFN have been shown to have both anti-tumor effects in the treatment of Kaposi sarcoma and anti-viral effects leading to reduction in HIV-RNA levels in patients with high CD4 T cell counts." (PMID 24603698, 2014). "Kaposi sarcoma risks among non-users of HAART steeply increased with decreasing CD4 cell count (HR for <50 vs ⩾350 cells μl−1, 12.85; 95% CI, 9.59–17.23)." (PMID 18665172, 2008). "After controlling for CD4+ cell count, adult on HAART had a significantly lower risk of oral Kaposi's sarcoma compared with those not on HAART (adjusted OR = 0.29; 95% CI = 0.10–0.89; p < 0.03)." (PMID 16916469, 2006). "Kaposi's sarcoma (KS) usually occurs in late stages of HIV infection, but it can happen in any CD4 count or HIV viral load." (PMID 37496761, 2023). "While globally the incidence of Kaposi sarcoma is decreasing with increasing ART coverage, we observed increasing prevalence over time, reaching 3.6% among patients enrolled in 2014 with low CD4 count, most likely due to improved detection, although the limitations of physician-diagnosis are known." (PMID 28719610, 2017). "Simultaneous diagnosis of neuromeningeal cryptococcosis and Kaposi’s sarcoma is not surprising in a patient with HIV infection and low CD4 counts, although this is rarely reported." (PMID 30867046, 2019).
Lymphadenopathy (80 papers, 2007 to 2025). Enlargement (swelling) of a lymph node. "In results, we identified the CD4+ T cell ratio as an independent predictor of malignancy in HIV-associated lymphadenopathy." (PMID 41179889, 2025). "We therefore excluded CD4+ or CD8+ cells as a causative cell type for Regnase-3 knockout-driven lymphadenopathy." (PMID 31126966, 2019). "In pre- and early Highly Active Antiretroviral Therapy (HAART) studies, the most common cause of lymphadenopathy (as seen on imaging) for an HIV patient with a CD4 count less than 50 cells/μL is mycobacterial infection." (PMID 24358876, 2013). "Severe immunosuppression and CD4 count <200 cells/mm3 were significantly associated with the presence of mediastinal lymphadenopathy." (PMID 23431432, 2013). "In the logistic regression model for predicting a diagnosis of malignancy, the following covariates were included: age, ethnicity, HIV risk factor, absolute CD4 count, parenchymal CT findings, presence of extrathoracic lymphadenopathy, lymph node maximum size and presence of necrotic lymph nodes." (PMID 24471994, 2014). "There is a close correlation between the occurrence of superficial lymphadenopathy and the CD4+ T cell count." (PMID 41179889, 2025). "A low number of CD4+ILT4+tolerogenic myeloid dendritic cells was correlated with lymphadenopathy as an initial clinical manifestation." (PMID 40746545, 2025). "Despite impaired CD4+ T cell activation, Atg5ΔOX40 mice developed lymphadenopathy and exhibited increased T cell numbers, pointing to a defect in immune regulation." (PMID 40977681, 2025). "We report a case of an HIV patient who presented with mild pleural effusion, multiple mediastinal, axillary lymphadenopathy with a low CD4:CD8 lymphocyte ratio, and favored clinically disseminated tuberculosis." (PMID 39398733, 2024). "Patients’ clinical presentations, CD4 counts, imaging features and PET metabolic parameters are helpful to identify the possible cause of lymphadenopathy." (PMID 36776334, 2023). "Only one patient presented with a necrotic lymphadenopathy, possibly related to his relative immunocompetence (295 CD4/mm3)." (PMID 37839020, 2023). "In that case, which was published in 1999, a 32-year-old female patient with newly diagnosed HIV infection and CD4 counts 416 cells/mm3 presented with painful supraclavicular lymphadenopathy." (PMID 35241027, 2022). "Impaired Fas function in effector CD4 or CD8 single-positive (SP) T cells causes the accumulation of B220+ CD4–CD8– double-negative (DN) TCRαβ+ T cells and, ultimately, splenomegaly and lymphadenopathy." (PMID 36248812, 2022). "Sézary syndrome is an aggressive leukemic variant of cutaneous T-cell lymphomas, characterized by erythroderma, lymphadenopathy, and peripheral blood involvement by CD4+ malignant T-cells." (PMID 35055124, 2022). "An intriguing finding was the fact that superficial lymphadenopathies >2 cm became significantly less frequent over time, whereas lymphadenopathies <2 cm became more frequent, while median CD4 count remain stable all along." (PMID 33628743, 2020). "The mean number of CD4 T lymphocytes in the seven patients with IgM anti-Toxoplasma antibodies and striking lymphadenopathy was 418.3 ± 336.4 cells/μL." (PMID 31690039, 2019). "Our results indicate that autoreactive CD4+ T-cells in axillary lymphadenopathy of DNFB-sensitised mice produce increased levels of IFN-γ and IL-17 in NC.h2b/b compared with NC/Nga." (PMID 29416104, 2018). "Only 10% of patients in their cohort had cavitary disease, but those with CD4 <200 cells/mm3 were significantly less likely to have cavities and more likely to have hilar/mediastinal lymphadenopathy." (PMID 24040132, 2013). "Disease appeared to be driven by the CD4 compartment since depletion of CD4 T cells from birth effectively prevented lymphadenopathy and tissue infiltration." (PMID 23849743, 2013).
Lymphadenopathy (continued). "These patients were also more likely to have intermittent fever, subcutaneous nodules and abscesses, generalized lymphadenopathy, bone ache, leukocytosis, and normal CD4/CD8 ratio (>0.5)." (PMID 24094273, 2013). "In the third case, rapidly progressive KS lesions with lymphadenopathy and tissue swelling occurred in a patient during anti-retroviral treatment, despite an increased CD4+ lymphocyte count and decreased HIV-1 level and KS-associated herpes virus replication." (PMID 21791047, 2011). "Drug-induced pseudolymphomas can also mimic more advanced CTCL presentations like Sezary syndrome, which may include erythroderma and lymphadenopathy, and circulating atypical CD4 T-cells with dense epidermotropic infiltrates histologically." (PMID 41550319, 2025). "The incidence of lymphadenopathy is negatively correlated with CD4 counts." (PMID 36776334, 2023). "Thus, candidate factors such as skin lesions, AST level, ALT ratio index, peripheral or abdominal lymphadenopathy, and CD4+ T-cell counts were all considered in different prediction models." (PMID 37367583, 2023). "Thus, CRF63_02A6 infection is characterized by more severe primary symptoms, such as prolonged fever, generalized lymphadenopathy, higher (>107) viral load, and lower CD4 cell counts compared to patients with the sub-subtype A6 infection." (PMID 36118194, 2022). "Lymphadenopathy was detected in 17 of 20 (85%) CARD11(E626K)CD4-Cre;HBZ Tg mice." (PMID 36446869, 2022). "Even though the patient has low CD4 counts, the enlarged lymphadenopathies in patients with disseminated histoplasmosis may thus testify than an active “front line” is remaining." (PMID 33628743, 2020). "Splenic CD4+ T cells of Stim1/2Foxp3 mice also showed higher Ki-67 expression compared to WT control mice suggesting that enhanced T cell proliferation contributes to the splenomegaly and lymphadenopathy of Stim1/2Foxp3 mice." (PMID 30862784, 2019). "HoipΔFoxp3 mice exhibited severe immune pathology, including lymphadenopathy, lymphocytic perivascular infiltration and tissue destruction of the lung, liver and exocrine pancreas, hyper-IgE production and abnormally high numbers of activated CD4+ and CD8+ T cells (CD44highCD62LlowKI-67+)." (PMID 27857075, 2016). "However, the fact that the delay between symptoms’ onset and diagnosis was longer in those with superficial lymphadenopathies >2 cm than in those without, and that their CD4 count was higher was consistent with the observation that deep lymphadenopathies were associated with less mortality." (PMID 33628743, 2020). "We also found that lymphadenopathy and the numbers of plasma cells, CD4−CD8−, and CD4+ T cells decreased in mice treated with the shAtg5-lentivirus." (PMID 32462028, 2020). "Statistical analysis of the CD4 T lymphocyte counts showed a significantly lower number (p = 0.0005) of CD4 T cells in patients with PGL than in patients without lymphadenopathy." (PMID 31690039, 2019). "The number of CD4 T cells in patients with PGL was significantly lower than that in patients without lymphadenopathy." (PMID 31690039, 2019). "In patients without signs of lymphadenopathy, the mean number of CD4 T cells was higher (958.1 ± 430.5/μL of blood), ranging from 184 to 1440 per μL of blood." (PMID 31690039, 2019). "Analysis of the number of CD4 T lymphocytes showed a significantly lower number of CD4 cells in patients with PGL than in those who were not suffering from lymphadenopathy." (PMID 31690039, 2019). "Disseminated NTM infection should always be one of the differential diagnosis for patients with fever or lymphadenopathy (both of which were observed in more than 50% of patients with unmasking IRS) after initiation of ART, especially in those with CD4 count less than 200/μl." (PMID 26985832, 2016).
Lymphadenopathy (continued). "In the different lymphocyte subgroups, a decrease in CD4+ natural killer T (NKT) cells was significantly correlated with increased metabolic activity in the pulmonary opacities, whereas a decrease in CD3+ and CD8+ NKT cells was correlated with increased metabolic activity in lymphadenopathy." (PMID 40659713, 2025). "Compared to the proliferative pattern, the necrotizing pattern exhibited a trend toward a longer duration from the onset of lymphadenopathy to lymph node biopsy, although not statistically significant, and a significant decrease in CD4‐positive cell count in the lesions." (PMID 39961627, 2025). "These patients had greater CD4 counts than those without superficial lymphadenopathies >2 cm." (PMID 33628743, 2020). "However, these patients had greater CD4 counts than those without superficial lymphadenopathies >2 cm." (PMID 33628743, 2020). "All those who developed HL had B symptoms and/or new palpable lymphadenopathy, suggesting that CD4 count monitoring if performed less frequently, or not at all, among those virologically suppressed individuals with CD4 counts >350 may not have delayed diagnosis." (PMID 24504076, 2014). "STAT3 GOF mice also developed lymphadenopathy as they reached maturity, with a reduction in the CD8 T cell frequency but overall increased numbers of CD4, CD8, and CD19 lymphocytes (data not shown)." (PMID 36136607, 2022). "Murayama and colleagues reported significant increase of CD3+CD4+CD20+ T cells in lymph nodes and not in blood during SIV infection in MAC at the stage of lymphadenopathy." (PMID 34220857, 2021). "In fact, BCL2(Tg)/lpr-transgenic mice exhibit substantially enhanced lymphadenopathy compared with lpr or BCL2(Tg) only mice, which is mainly explained by the enhanced accumulation of both immature double negative (CD4−/CD8−) and double positive (CD4+/CD8+) T-cells." (PMID 27206675, 2016).